PKM (pyruvate kinase M1/2)
Diseases named in the same sentence as PKM in open-access papers (continued):
Sharing a sentence is not in itself a finding about the gene and the disease.
tumor (continued). "However, administration with the inhibitor of PKM, shikonin, decreased the tumor volume of TET2-cas9 group, and increased the survival rate." (PMID 32774157, 2020). "Knockdown PKM could inhibit proliferation and lead to apoptosis in several different types of tumor cells." (PMID 31956955, 2020). "Thus, these precise molecular mechanisms used to define the roles of PKM splicing and subsequent PKM2 formation on tumor initiation and development provide a new direction for exploring the relationship between PKM2 and LncRNAs." (PMID 31654067, 2019). "Analysis of the TCGA AML cohort (TCGA, NEJM, 2012) indicated that patients exhibiting high PKM and G6PD levels exhibit a bad prognosis and lower overall survival, confirming that overexpression of these metabolic enzymes is linked to tumor growth and leukemia expansion." (PMID 31623164, 2019). "We checked the expression profile of PKM isoforms in normal and 3MC induced-tumor tissues." (PMID 26911935, 2016). "Interestingly, in fast-proliferating and tumor cells, the PKM isoform can be switched from PKM1 to PKM2, a switch associated with a reduced pyruvate kinase activity." (PMID 26992222, 2016). "Also, it has been thought that tumor cells switch their PKM isoform from PKM1 to PKM2 during tumor development." (PMID 25721733, 2015). "In addition, we demonstrate that overexpression of PKM2 in most tumor types is regulated by hypomethylation of intron 1 near the PKM gene promoter." (PMID 24077665, 2014). "Although high PKM2 expression and low PK activity are considered defining features of tumors, very little is known about how PKM expression and PK activity change along the continuum from low grade to high grade tumors, and how these changes relate to tumor growth." (PMID 23451252, 2013). "Moreover, SMAR1 suppresses in vivo tumor formation via the regulation of PKM isoform expression." (PMID 33863392, 2021). "Some interesting genes were identified as correlation-enhancing genes—PKM: pyruvate kinase and repressing genes; COX5B: cytochrome c oxidase subunit 5B in rS-pS —indicating a possibility of alterations of mRNA-to-protein correlation of the energy metabolism–associated genes in the tumor." (PMID 33384992, 2020). "Independent of EGFR-mediated MAPK/AKT signaling, PKM phosphorylation was highly ranked in approximately half of our ccRCC tumor cohort and associated with lower tumor grade (p < 0.05), reflecting a secondary, EGFR-mediated mechanism of glycolytic reprogramming in a subset of ccRCC tumors." (PMID 31675502, 2019). "The HOXB-AS3 peptide suppressed CRC growth through blocking hnRNPA1-mediated PKM splicing, thereby inhibiting the formation PKM2 and suppressing the reprogramming of the glucose metabolism; this suggests that PKM2-associated HOXB-AS3 has a role in tumor formation and progression." (PMID 31654067, 2019). "Interestingly, highly proliferative stem-cells such as ESCs and tumor cells exhibit preferential transcription of PKM2—indicating that PKM may play an important role in the process of stem-cell metabolic reprogramming." (PMID 24567722, 2014). "Thus, decreased methylation in intron 1 of PKM gene near its promoter may contribute to increased PKM expression in tumor tissues." (PMID 24077665, 2014). "This activation releases proliferative signals and enhances the transcription of splicing factors, leading to the splicing of the PKM transcript into the PKM2 isoform and ultimately mediating metabolic reprogramming in tumor cells." (PMID 40721814, 2025). "When HNRNPA1 cannot be lactylated, the balance of PKM splicing shifts, resulting in more PKM1 and less PKM2, which in turn dampens glycolytic flux and tumor growth." (PMID 41275207, 2025). "PKM2, an isoform of PKM, predominantly expressed in embryonic cells, stem cells, and tumor cells characterized by heightened anabolic requirements, is a crucial enzyme in the metabolic process of aerobic glycolysis in neoplastic growths." (PMID 39820532, 2025).
tumor (continued). "Glycolysis genes HK1, GAPDH, ENO1, LDHA, and PKM, and cell cycle genes (except CCND2) were among the most tumor-specific genes." (PMID 39774001, 2025). "Volcano plot analysis of differentially expressed genes showed that NDRG1 is markedly upregulated in tumor tissues, alongside several key metabolic genes, including LDHA, SLC16A1, PKM, HK1, and LDHB." (PMID 40539245, 2025). "The cleavable isotope-coded affinity tags (cICAT) analysis identified 68 proteins, with 5 overexpressed in tumor samples: S100A11, HNRNP, MIF, PIGR precursor, and PKM." (PMID 39194522, 2024). "Integration with metabolomic data obtained from the same samples revealed mitochondrial dysfunction in tumour tissue through deregulation of OGDH, SDH family enzymes and PKM." (PMID 38969985, 2024). "The integration of proteomic and metabolomic data from NAT and TT using ocEAn, showed that both proteomic datasets are coherent with a tumour tissue displaying mitochondrial dysfunction, notably with deregulations of OGDH, SDH family enzymes and PKM." (PMID 38969985, 2024). "In distinguishing between tumor and normal nodules, the following five proteins showed the best performance: P50479 (PDLIM4), P04083 (ANXA1), P14618 (PKM), P61916 (NPC2), and P02545 (LMNA)." (PMID 36418670, 2023). "In particular, we identified a specific signature of glycolysis-related genes in BRAF-like tumours, which display the overexpression of SLC2A1, SLC2A3, HK3, PFKFB3, PKM, LDHA and SLC16A3 (alias Mct4, the membrane channel regulating lactate efflux)." (PMID 37198319, 2023). "Through the regulation of pyruvate kinase (PKM) splicing and the subsequent increase in PKM2 expression, hnRNPA2B1 exerts a tumor-suppressive effect on cellular glucose metabolism." (PMID 37546413, 2023). "It has been reported that miRNAs target proliferation-related genes and proteins, such as PKM, Akt, and MEF2D, to regulate tumor cell proliferation." (PMID 36172186, 2022). "Of the four PKM isoforms, PKM1 is found in high-energy demanding tissues, while PKM2 is expressed mainly in high proliferating cells like embryonic tissue and tumor cells." (PMID 35890106, 2022). "Under the action of shear factors, mRNA transcribed by PKM can form PKM1 containing exon 9, which is usually expressed in normal tissues, and PKM2 containing exon 10, mainly expressed in embryonic cells and tumor cells." (PMID 35408903, 2022). "The upregulated SLC2A1 (GLUT1) (T/TA = 9.49), HK2 (T/TA = 36.69), PFKP (T/TA = 15.97), PKM (T/TA = 4.08), and LDHA (T/TA = 8.58) suggested the increased of glucose utilization for lactate fermentation in ccRCC tumor vs. adjacent tissues." (PMID 35440542, 2022). "Next, we examined the expression of key enzymes catalysing glycolysis such as PFKP, ENO1, PKM and LDHA in ccRCC tumours and the matched controls." (PMID 35672925, 2022). "For example, the splicing type of Ras and CyclinD1 determines the rate of tumor cell proliferation, PKM alternative splicing changes the type of metabolism, and MDM4 and MDM2 protein isoforms regulate tumor sensitivity to therapy." (PMID 35538281, 2022). "PKM, ENO2, and SLC16A3 have been researched to have important effects on promoting tumor progression." (PMID 36245978, 2022). "Other examples from this study include well-described tumor-promoting genes such as SRSF2, DNMT3A, ATM, BRCA1 and PKM, for which Tax- and HBZ-alternative splicing events are now associated with ATLL for the first time." (PMID 34543356, 2021). "They found that this compound regulates glucose metabolism in tumor cells and significantly reduces lactate production through interaction with glycolytic enzymes such as aldolase C (ALDOC), LDHB, GAPDH, and PKM." (PMID 34434922, 2021). "These two isoforms result from mutually exclusive alternative splicing of PKM pre-mRNA, reflecting the inclusion of either exon 9 (PKM1) or exon 10 (PKM2), required for tumor cell proliferation." (PMID 33573689, 2021).
tumor (continued). "In a previous study in metastatic colorectal cancer, we found mRNA tumor overexpression of GLUT-1 and the glycolytic genes hexokinase 1 (HK-1) and 2 (HK-2), pyruvate kinase isoform 2 (PKM-2) and lactate dehydrogenase isoform A (LDH-A)." (PMID 32372141, 2020). "In turn, HIF-1α is conducive to the adjustment of tumors to hypoxia through transcriptional activation of more than 100 downstream genes including LEP, EPO, PKM, etc.; in this regard, HIF-1α further promotes the proliferation of tumor cells." (PMID 33681184, 2020). "Inhibitors of glucose transporters, PKM-2 and LDH-A, attenuate aerobic glycolysis and tumor proliferation with the potential therapeutic role, alone or in combination with anti-angiogenic and immune checkpoint therapies." (PMID 32372141, 2020). "In contrast, HUH7 cells showed a higher expression of 98 metabolic targets upregulated in tumours (e.g. HK2, PKM, PSPH, GLUL, ASNS, and fatty acid synthesis enzymes ACLY, FASN)." (PMID 30176945, 2018). "The alternative splicing of PKM has been controversial for a long time, but many scientists now tend to approve the increase of PKM2 expression in tumor." (PMID 29299177, 2017). "PKM is a highly expressed gene with a RSEM value of more than 10,000 in both normal and tumor tissues of each organ, except the liver." (PMID 25738776, 2015). "We set out to determine if the increased splicing factors and subsequent alternative splicing of PKM, resulting in a high PKM2/PKM1 ratio, correlated with glycolytic metabolism in these tumor cells." (PMID 25970789, 2015). "Although PKM-ASO monotherapy had a limited effect in an immunodeficient mouse model of PDAC, synergy between PKM-ASO and anti-CTLA-4 immune checkpoint blockade (ICB), which targets Tregs, restricted tumor growth in an immunocompetent mouse model." (PMID 42009652, 2026). "Additionally, Bone Morphogenetic Protein 4 (BMP4) directly binds to the PKM promoter via SMAD5, upregulating PKM2 expression and enhancing glycolytic flux, thereby promoting glucose metabolism reprogramming and tumor progression." (PMID 41169372, 2025). "To verify whether TREM2+ macrophages regulate the expression of PKM, G6PD, and ALDOA in tumor cells, we detected their levels in Hepa 1–6 cells treated with CM from WT or Trem2−/− BMDMs." (PMID 39838454, 2025). "Among these genes, PKM, CAV1, GLI3, PICK1, PRPF6, and UBE3A have been identified as oncogenes, and play a pivotal role in orchestrating tumor-host interactions, fostering tumor growth, promoting metastasis, enhancing resistance to therapy, and ensuring cellular survival." (PMID 38280969, 2024). "Unlike previous findings that Hsp90 influences tumor progression by regulating the abundance of PKM,[16a] we found that the differential expression of Hsp90 did not affect the expression and activity of metabolic enzymes in MGC803 and HGC27." (PMID 38874476, 2024). "Notably, proteins like Heat shock 70 kDa protein 1A/1B, Pyruvate kinase PKM, and Phosphoglycerate kinase 1 were suggested to be differentially regulated in OSCC patients, with implications for oral carcinogenesis and tumor growth." (PMID 39456901, 2024). "While the extracellular tumor-linked roles of PGAM1, LDHA, PKM, TPI1, and PGK1 have not been tested, the anti-tumor actions of ALDOA 13, 18, ENO1 16, 18, and GAPDH 20 were reported." (PMID 37056934, 2023). "In vivo, the knockdown cells (as compared to SH-control transduced cells) shuttled EVs lacking SNHG3, thereby decreasing PKM expression, which resulted in inhibited tumor proliferation, heightened intratumoral pH, and decreased lactate levels." (PMID 35563739, 2022). "Pyruvate kinase (PKM) has two isomers, namely, PKM1 and PKM2, and exists as PKM2 in tumor tissues." (PMID 35252177, 2022). "Of the remaining 41 genes, three (PIGC, PKM and PPIB) were commonly upregulated with oncogenic potential and 31 were commonly downregulated among CP and PDAC-CP, of which, 3 (AZGP1, EGLN1 and GNMT) were tumour suppressors." (PMID 35854233, 2022).
tumor (continued). "In addition, we also identified significant up-regulation of Hyp on glycolysis enzymes pyruvate kinase (PKM), enolase (ENO1), and autophagy protein Parkin (PARK7) in tumor tissue." (PMID 36026437, 2022). "Moreover, IHC staining of PKM isoforms revealed that PKM2 expression was elevated and PKM1 expression was significantly low in tumor samples compared with that of normal control tissue." (PMID 33863392, 2021). "In this study, we identified several metabolic enzymes with higher abundance due to knockdown of CA1 mRNA that may play an important role in tumour progression: TPI, protein‐glutamine‐gamma‐glutamyltransferase 2, peroxidasin homolog and pyruvate kinase (PKM)." (PMID 30916466, 2019). "It is found that oleanolic acid (OA) alternatively splices initial PKM transcriptional mRNA to produce more PKM1 instead of PKM2 by blocking mTOR signaling pathways or c-Myc-dependent hnRNPAl, which abrogates Warburg effect in tumor cells." (PMID 29299177, 2017). "PKM2 expression significantly increased in 13 tumor types, and did not significantly decrease in any of the tumors, similar to PKM." (PMID 25738776, 2015). "Moreover, the activation of key enzymes such as PKM and LDHA indicates that UBD may accelerate tumor cell energy metabolism by promoting lactate production in the downstream steps of glycolysis." (PMID 40692714, 2025). "Moreover, RNA sequencing (RNA-seq) using tumor tissues from the Alb-Cre;S225Kfl/fl and S225Kfl/fl groups showed that SIX1 S225K knock-in regulated expression of many genes, including the glycolytic genes LDHA, ENO1, and PKM." (PMID 39617783, 2024). "Moreover, ongoing studies target the identified genes (ENO1, STMN1, PKM, CDK1), with therapies like enolase 1 depletion demonstrating efficacy across various tumor types by inhibiting glycolysis, growth, proliferation, migration, metastasis, and sensitizing tumors to chemotherapy and radiotherapy." (PMID 38840205, 2024). "We also analyzed the transcriptomics datasets from TCGA primary tumor samples (10,496 cases in total) and GTEX normal tissue samples (7,792 cases in total) from UCSD Xena, and found that the expression level of galectin-3 was correlated with that of HK2 and PKM in all data." (PMID 36481721, 2022). "Further, an increase in tumor growth and proliferation efficiency in OPM-BMG tumors correlated well with the downregulation of activated AMPK (p-AMPK) coupled with HK-II, Glut-1, and PKM-2, leading to glycolytic up-regulation compared to its parental phenotype." (PMID 36591481, 2022). "Thus, increased expression of PKM and LDHA in CACs might be resulting in the tumor cell survival by preventing the entry of glycolytic pathway into feedback inhibition loop by the end product of the pathway." (PMID 29568375, 2018). "In addition, through assaying the level change and the effect on secretion exosomes of PKM1, we found that pyruvate kinase activity of PKM might be not relevant to tumour cell exosome secretion." (PMID 28067230, 2017). "Proteins that were perturbed in expression level in the peripheral or in the central part of the tumor as compared with the non-involved part included S100A11, HNRNPF, HNRNPH1 or HNRNPH2, GSTP1, PKM and FABP1." (PMID 34563043, 2021). "We observed the BORIS enrichment at PKM exon-10 and no change at exon-9 and 11 in HNC tumor tissue compared with the paired normal." (PMID 31675998, 2019).
infection (32 papers, 2011 to 2026). The state of being infected such as from the introduction of a foreign agent such as serum, vaccine, antigenic substance or organism. "In our mouse model, we detected PKM, the expression of which increased persistently at all stages of infection." (PMID 39625960, 2024). "SVA infection in mice increased expression of PKM and PGK1 in tissues and serum yields of lactate." (PMID 37126525, 2023). "Western blot analysis verified three selected proteins involved in glycometabolism pathways, namely PGM1, PKM, and PGK1 were increase over time post the infection." (PMID 35869254, 2022). "The elevated expression of PGM1, PKM, and PGK1 accelerate the glycolysis pathway; thus, we speculated that the B. pseudomallei HNBP001 infection accelerated glucose uptake in host cells." (PMID 35869254, 2022). "This was more likely due to the large consumption of pyruvate for multiple pathways rather than the blocking of pyruvate generation since the transcription level of pyruvate kinase PKM, which converts PEP to pyruvate, was significantly induced in both DF-1 cells and LMH cells upon ILTV infection." (PMID 32833996, 2020).
digestive system tumors (3 papers, 2022 to 2025). "GI tumor tissues with higher CBX3 K10la intensities exhibited elevated protein levels of hexokinase 2 (HK2), glucose‐6‐phosphate isomerase (GPI), and pyruvate kinase M (PKM)." (PMID 39018247, 2024).
neurological disease (3 papers, 2024 to 2025). "PYG serves as the rate-limiting enzyme in glycogenolysis, while PKM and HK are crucial glycolytic enzymes that regulate the rate of glycolysis and are implicated in various neurological disorders." (PMID 39199268, 2024).
bacterial infection (2 papers, 2022). "In summary, pathogenic bacterial infection upregulated PKM, LDHB, LDHA, ALDOA, PGD, GPI, and ALDOC, increased ATP production, which promotes leukocyte recruitment and NALP3-inflammasome activation, increases NADPH production, and promotes ROIs modulating inflammation and injury." (PMID 36335251, 2022).
PKM also shares sentences with these, for which no sentence is quoted: non-small cell lung carcinoma (40 papers); lung adenocarcinoma (34); esophageal squamous cell carcinoma (28); diabetic nephropathy (23); osteosarcoma (23); Alzheimer disease (19); liver fibrosis (19); colitis (18); lymph node metastasis (15); coronary artery disease (14); Hyperglycemia (13); renal carcinoma (13); renal cell carcinoma (13); renal fibrosis (13); cardiovascular diseases (12); esophageal cancer (12); head and neck squamous cell carcinoma (12); Insulin resistance (12); brain tumor (11); metabolic disease (11); myocardial infarction (11); ischemic stroke (10); Stroke (10); acute kidney injury (9); endotoxemia (9); ischemia (9); oral squamous cell carcinoma (9); autoimmune disease (8); Autoimmunity (8); Hepatic steatosis (8).
A further 241 diseases each share a sentence with PKM in 8 papers or fewer.